TLR7 (toll like receptor 7)
Diseases named in the same sentence as TLR7 in open-access papers (continued):
Sharing a sentence is not in itself a finding about the gene and the disease.
lupus (continued). "Taken together, the combination of TLR7/TLR8 activation and lupus susceptibility genes expressed in TC mice functionally breached the gut barrier and decreased the expression of tight junction proteins." (PMID 37483626, 2023). "Loss-of-function mutations in TLR7 are a genetic risk factor for the development of COVID-19 pneumonia, whereas gain-of-function mutations in TLR7 and TLR8 drive immune disorders such as systemic lupus erythematosus." (PMID 37462944, 2023). "Repeated epicutaneous application of the TLR7 agonist to wild-type mice leads to lupus-like features, including mild LN." (PMID 37894915, 2023). "Murine models of lupus have provided genetic and experimental evidence to support a role for TLR7 activation in LN pathogenesis." (PMID 37894915, 2023). "The importance of TLR7 signaling in the production of autoantibodies in lupus-prone mice is demonstrated by the autoantibody production that occurs with TLR7 inhibition." (PMID 37744368, 2023). "These CD11b+CD11c+T-Bet + cells are increased in various mouse models of lupus, including Mer−/− and SWEF-deficient mice; these cells are also especially sensitive to TLR7 and differentiate into autoantibody-secreting cells." (PMID 36875095, 2023). "Here, we investigated the intestinal immune response, microbiota composition, and intestinal barrier integrity in a TLR7-mediated lupus model." (PMID 37346043, 2023). "In TLR7-induced lupus, PADI2 and PADI4 promote the induction of TLR7 in lupus through innate and adaptive immunity." (PMID 37020554, 2023). "With this background, important steps toward deciphering the TLR7/9 paradox and toward gaining a greater understanding of how TLR7 promotes disease in lupus involve understanding TLR7’s roles in different cell types in a single model." (PMID 37606042, 2023). "The contextual linking words indicate why the model suggested IRAK4 for lupus, due to its involvement in innate immunity through TLR7 that subsequently activates Myd8841,42." (PMID 37225853, 2023). "The two lupus-prone mouse strains in which the spontaneous translocation of pathobionts has been documented either carry the Yaa locus or a Tlr7 transgene." (PMID 37483626, 2023). "Its role in the development of autoimmunity was established with the aid of murine models, where the expression of two copies of Tlr7 or Tlr8 was sufficient to induce lupus-like manifestations." (PMID 37723501, 2023). "In lupus, nucleic acid–containing complexes in the serum were observed to activate the nucleic acid–recognizing TLRs, i.e., TLR7 and TLR9, which are chiefly expressed by immune cells." (PMID 36719379, 2023). "The activation of the TLR7 expressed in distinct cells induces NFκB pathway, bringing about varied inflammatory or immune disorders such as lupus, atherosclerotic plaques and autoimmunity." (PMID 37780385, 2023). "The promotion of a lupus phenotype by TLR7 is supported by the fact that a mouse strain with the yaa translocation and therefore an additional copy of TLR7 developed accelerated symptoms of lupus pathology and anti-DNA autoantibodies." (PMID 36648888, 2023). "Further studies focus on the evaluation of its potential efficacy in patients with autoimmune diseases, such as lupus, with high TLR7 and TLR8 expression." (PMID 36677692, 2023). "The expression of TLR7 is critical in controlling sex-specific differences observed in mice on a lupus-prone background, as a dual TLR7 expression in male lupus mice results in higher ABCs formation and more severe organ damage." (PMID 36817481, 2023). "But in mice, numerous studies have shown that TLR7 signaling is central to the lupus phenotype, whereas knockout of TLR9 alone has only subtle effects on autoantibody specificity or exacerbated disease." (PMID 37555846, 2023). "We crossed BAFF-RFP reporter mice with two spontaneous mouse lupus models: Tlr7 Tg mice and Sle1 mice." (PMID 36923413, 2023).
lupus (continued). "It is known that pDCs potently produce type I IFNs in response to ligation of nucleic acid–sensing pattern recognition receptors (PRRs), such as TLR7 and TLR9, which have been implicated in lupus development." (PMID 36853827, 2023). "Using this model, we found in this study that activation of the TLR7/8 pathway impaired gut permeability, but only in the presence of a lupus-prone genetic background." (PMID 37483626, 2023). "The pathogenic role of TLR7 and the regulatory role of TLR9 in pDCs have been demonstrated in spontaneous murine models of lupus and PIL." (PMID 36853827, 2023). "Murine lupus models, such as the pristane-induced lupus model, depend on TLR7 signaling for lupus pathogenesis." (PMID 37894915, 2023). "The patient with lupus symptoms confirms the direct link between TLR7 and human B cell autoimmunity." (PMID 36648888, 2023). "Consistently, the genetic ablation of TLR7 abolished the development of spontaneous germinal centers in murine lupus models coinciding with amelioration of pathogenesis in these models." (PMID 36648888, 2023). "Recently, Toll-like receptor (TLR7) signaling was demonstrated to play an important role in the development of lupus." (PMID 36992490, 2023). "Here, we investigated the consequences of the intestinal inflammation in a TLR7-mediated lupus model." (PMID 37346043, 2023). "In a TLR7-mediated lupus model, we investigated the consequences of the intestinal epithelial barrier disruption throughout the course of disease on the systemic humoral immune response to commensals." (PMID 37346043, 2023). "We establish the importance of TLR7 and guanosine-containing self-ligands for human lupus pathogenesis, which paves the way for therapeutic TLR7 or MyD88 inhibition." (PMID 35477763, 2022). "In a similar model the gut microbiome plays an essential role in the induction of lupus by stimulating TLR7." (PMID 35968787, 2022). "MRL/lpr lupus mice that lack TLR7 exhibit disease amelioration and diminished antibodies against RNA-associated antigens." (PMID 36591307, 2022). "For example, resiquimod, Toll-like receptor 7/8 agonist, induced lupus model which were TLR7/9- dependent mice lupus models." (PMID 35677055, 2022). "TLR8 knockout mice have high endogenous TLR7 expression and activity that promotes a lupus-like phenotype." (PMID 35874527, 2022). "The mystery of why deletion of TLR9 in lupus prone mice leads to exacerbation of SLE was resolved by studying the correlation between TLR7 and TLR9." (PMID 36389822, 2022). "Interplay between RUBICON, RNA trafficking, and TLR7 signaling in lupus is, thus, an intriguing possibility suggested by our data." (PMID 35192551, 2022). "In the current study, we demonstrate an informative activation cascade inducing lupus serological and pathological findings inside B cells from splenocytes after TLR7 epicutaneous stimulation." (PMID 36359746, 2022). "An imiquimod (IMQ)-induced lupus model was used to analyze the lupus mechanism related to the aberrant TLR7 signals." (PMID 35371102, 2022). "On the other hand, the deletion of TLR7 reduces the development of lupus in strains that spontaneously develop the disease." (PMID 36210830, 2022). "Rommler found that agonists of TLR7 or TLR9 activated pDCs in lupus patients, even in healthy people, to induce a large amount of IFNα and immune overactivation." (PMID 36555668, 2022). "We previously showed that in the BXD2 mouse model of lupus, transitional B cell endogenous IFNβ was the initial step enabling assembly and efficient signaling through TLR7." (PMID 35436902, 2022). "The aim of this study is to utilize a model mimicking viral infection that targets TLR7, to determine the B cells’ role in lupus and check the role of the mitochondrion in B-cell activity." (PMID 36359746, 2022). "In in vivo experiments, TLR7 agonist-induced lupus mice and aPL-expedited inferior vena cava thrombosis mice were administered 6-gingerol at a dose of 10 mg/kg/day." (PMID 36133811, 2022).
lupus (continued). "A lupus-prone mouse strain, the Y-linked autoimmune accelerator strain, has an additional copy of the TLR7 gene that results in TLR7 hyperactivation, leading to lupus-like state." (PMID 35812450, 2022). "EBV enhances the TLR7 pathway in humans and drives the T helper 17 cell-related pathway in the lupus mouse model." (PMID 36359746, 2022). "Primary studies using different lupus-prone mouse strains crossed to TLR7- or TLR9-deficient mice, revealed that depletion of TLR7 ameliorates SLE, while surprisingly ablation of TLR9 exacerbates the disease." (PMID 36389822, 2022). "In the hydrocarbon oil-induced systemic lupus erythematosus (SLE) murine model, IL-1R8-deficiency was associated with unleashed TLR-7-mediated activation of DCs and consequent more severe autoimmune tissue injury." (PMID 35211118, 2022). "It has recently been shown that the ABC female sex bias in lupus mice is abolished following the duplication of Tlr7 in male mice." (PMID 36477199, 2022). "Here, we showed that TLR7 activation induced myocytolysis in both lupus-prone and control mice, but a microvascular inflammation of the heart was observed only in lupus-prone TC mice, with features similar to antibody-mediated rejection (AMR)." (PMID 35860280, 2022). "Skin lesions in lupus, also more common in females, are triggered by Th2 cells, which subsequently transition to a Th1-like phenotype as a result of increased TLR7 signaling." (PMID 36505451, 2022). "TLR7 activation accelerated full-blown lupus in young lupus prone TC mice characterized by the acute activation of innate and lymphoid cells, which accelerated cardiac hypertrophy." (PMID 35860280, 2022). "Here we report that acute TLR7 activation induces three types of lesions in the heart of lupus-prone TC mice: acute microvascular inflammation, myocytolysis with intracellular vacuolization and reactive myocardial hypertrophy." (PMID 35860280, 2022). "Most mouse lupus models in which TLR7 has a role in pathogenicity display increased formation of GCs and T follicular helper (TFH) cells and it has been proposed that TLR7 drives GCs enriched in self-reactive B cells." (PMID 35477763, 2022). "In the Tlr7 Tg model of lupus, dietary resistant starch reduced the translocation of L. reuteri by inducing the production of SCFA." (PMID 35795671, 2022). "TLR7 is a ssRNA sensor whose overexpression in normal mice is sufficient to induce a lupus phenotype." (PMID 35104241, 2022). "TLR7 and TLR9 single nucleotide polymorphisms (SNPs) have been linked to systemic lupus erythematosus in numerous studies (SLE)." (PMID 36439744, 2022). "Some studies have shown SCFAs as inconsequential in protecting against or ameliorating lupus, while beneficial effects have been observed in the TLR7-dependent lupus model." (PMID 35833129, 2022). "Of direct relevance to the current study, TLR7 is required for ABC expansion in the context of lupus, and B cells that express T-bet drive lupus-like disease in mice." (PMID 36591307, 2022). "We found that the NCF1 p.R90H variant facilitated endosomal cleavage and activation of TLR7 and TLR9 in the endosome, thereby boosting the TLR pathway and IFN-I production, which resulted in more serious autoimmune responses and aggravated lupus symptoms." (PMID 35788118, 2022). "The alleviation effect of inhibitory oligonucleotides of TLR9 has been confirmed, and TLR7 has also verified that it is one of the target molecules for lupus pathology." (PMID 36555668, 2022). "Corroborative studies in a lupus mouse model revealed that increasing TLR7 gene dosage augments production of autoantibodies directed against RNA." (PMID 36591307, 2022). "An intimate correlation between an elevated serum IFN-α in patients with active lupus and microbial infection TLR7/9, pDCs, and IFN-α were believed to interact with each other." (PMID 36555668, 2022). "In this study, its immunosuppressive effect as a TLR7 or TLR9 antagonist was investigated in a lupus mouse model." (PMID 36555668, 2022).
lupus (continued). "Although there is compelling evidence that TLR7 is integral to lupus pathogenesis, there is a relative paucity of studies examining this TLR in pSS." (PMID 36591307, 2022). "Lupus-prone mice with B-cell-specific Tlr7 deletion show inhibited B-cell responses, decreased levels of class-switched autoantibodies against RNA-associated autoantigens, and diminished systemic autoimmunity." (PMID 36220996, 2022). "It has been shown that the overexpression of TLR7 induces systemic autoimmunity in a lupus-prone mouse strain." (PMID 36210830, 2022). "Indeed, increased TLR7 signaling has been associated with SLE development both in humans and mice, while in various SLE mouse models depletion of TLR7 led to the amelioration or even prevention of lupus disease." (PMID 34108972, 2021). "In female NZBWF1 mice, which have multiple lupus susceptibility loci and weak IFN signature, dual TLR7 and TLR9 antagonism partially prevented the disease progression." (PMID 34573058, 2021). "In TLR8-knockout mice, TLR7 expression is upregulated and a lupus-like autoimmunity develops due to an increased TLR7 function." (PMID 34711839, 2021). "Inhibition of TLR7 represents a potential therapeutic strategy to reduce anti-RNA autoantibody production and attenuate glomerulonephritis in lupus mice." (PMID 33767707, 2021). "Another recent study reported that supplementation with a high fibre-rich diet improved lupus-related disease manifestations in a Toll-like receptor 7 (TLR7)-dependent lupus-like mouse model." (PMID 34335588, 2021). "IFNλs promote immune dysregulation and tissue inflammation in TLR7-induced lupus and regulate tissue inflammation through specifically affecting skin and kidney cells." (PMID 34149799, 2021). "Our group has investigated the involvement of gut microbiota in hypertension in a murine model of systemic lupus erythematosus induced by Toll-like receptor (TLR)-7 activation." (PMID 34573058, 2021). "A higher dosage of TLR7 is related to disease severity in lupus-prone mice, and TLR7 overexpression induced systemic autoimmunity even in non-lupus-prone mice." (PMID 34580371, 2021). "We demonstrated previously that in vivo TLR8 restrains TLR7 on DCs, and that TLR8ko mice on the C57BL/6 background develop spontaneous lupus due to increased TLR7 signaling by DCs, while TLR8ko B cells or macrophages retain normal TLR7 signaling." (PMID 34108972, 2021). "The TLR7 agonist imiquimod drives lupus nephritis in mice, whereas lupus nephritis spontaneously developed in the lupus-prone strain, New Zealand Black/New Zealand White F1 mice (NZBWF1 mice) is ameliorated by a small chemical TLR7 inhibitor." (PMID 34868046, 2021). "We chose to use R848 because TLR7 gene dosage is essential for the accelerated disease in the FcγRIIB−/−Yaa mice and TLR7 is important for pathogenesis in other mouse models of lupus." (PMID 34197340, 2021). "TLR7 plays a key role in the B response in lupus, the production of anti-ribonucleoprotein (RNP) autoantibodies, as well as in the production of type I IFN (IFN-I) by pDCs." (PMID 33498655, 2021). "In conclusion, we demonstrate for the first time that the chronic treatment with LC40 or BFM prevented hypertension and endothelial dysfunction in a mouse lupus model induced by TLR-7 activation." (PMID 34444829, 2021). "The generation of high-affinity autoantibodies and long-lived plasma cells in lupus is dependent on the development of a robust GC response, with TLR7 and TLR9 signaling in B cells likely being required for this response." (PMID 34197340, 2021). "In this TLR7-induced lupus murine model an increased production of IFN-λ was observed, while the deficiency of its receptor (IFN-λR1) significantly decreased the activation of not only the immune cells, but also of the keratinocytes and mesangial cells." (PMID 33916456, 2021).
lupus (continued). "Profiling colonic microbiomes from TLR7-dependent lupus mice showed an enrichment of mainly three bacterial taxa: the genera Bacteroides and Macellibacteroides, and the family Bacteroidaceae, whereas Acetobacteroides was enriched in CTR group." (PMID 34573058, 2021). "For example, lactobacillus reuteri colonizes lupus-prone hosts and translocates to mesenteric lymph nodes, liver, and spleen, and exacerbates TLR7-dependent lupus in conventional and germ-free mice." (PMID 34045965, 2021). "Our results demonstrate for the first time that the chronic treatment of the probiotics LC40 or BFM prevented hypertension and endothelial dysfunction in a mouse lupus model induced by TLR-7 activation." (PMID 34444829, 2021). "TLR7 is known to play a pivotal role in autoantibody production in murine lupus and is localized within the intracellular endosome along with TLR3 and TLR9." (PMID 34884569, 2021). "TLR4 engagement on mouse FDCs induces up-regulation of Fc receptors and integrins, while TLR7 on FDCs promotes auto-reactive B cells in a mouse model of systemic lupus erythematosus through secretion of IFN-α." (PMID 34424268, 2021). "In contrast, the association between clinical manifestations and TLR7, TLR8 and TLR9 polymorphisms is clear and the involvement of the endosomal TLRs, mainly TLR7, in lupus is backed up by several studies." (PMID 34572504, 2021). "In mice with Toll-like receptor-7 (TLR7) agonist imiquimod-induced lupus, a significant expansion of MDSCs induced podocyte injury through increasing ROS in lupus nephritis (LN)." (PMID 34282122, 2021). "TLR7 was overexpressed in models of severe lupus, and in patients with SLE, and the inhibition or attenuation of TLR7 signaling ameliorated the inflammatory response in the lung and kidney of lupus-prone mice." (PMID 33224145, 2020). "Toll-like receptor 7 (TLR7) and TLR9, which recognize single-stranded RNA and bacterial DNA, respectively, have been previously associated with lupus disease severity in mice." (PMID 32251357, 2020). "In contrast, the unique genes of the lupus group are more involved in pathogen recognition and degradation, such as TLR7, and FCGR2A." (PMID 33324666, 2020). "Pristane is a hydrocarbon oil that, when injected intraperitoneally, leads to a lupus-like phenotype by a toll-like receptor 7 (TLR7)-dependent mechanism." (PMID 33101313, 2020). "Mice harboring the Yaa chromosome are used as a male-specific lupus model in which IFN responses are enhanced due to TLR7 duplication." (PMID 32708595, 2020). "Overexpression of Tlr7 promotes autoimmunity through dendritic cell proliferation, whereas the deletion of Tlr7 in lupus-prone MRL/lpr mice diminishes autoantibody and immune activation." (PMID 33083760, 2020). "In summary, PAD4 promoted neutrophil infiltration into the kidneys and the development of nephritis in TLR7 agonist-induced lupus model mice." (PMID 32655553, 2020). "Interestingly, the key immune receptor TLR7 is linked to the pathophysiology of the autoimmune disorder systemic lupus erythematosus (SLE)." (PMID 33488596, 2020). "In summary, we investigated the effects of chronic exposure to a human-relevant dose of 17α-ethinyl estradiol on kidney disease and response to ssRNA viral (TLR7) or bacterial (TLR9) challenge in a mouse model of systemic lupus erythematosus." (PMID 32251357, 2020). "In a Tlr7 transgenic mice model of lupus induced by overexpression of Toll-like receptor 7, secretion of autoantibodies is reduced when autophagy is suppressed through knockout of the autophagy protein ATG5 in B cells." (PMID 33187196, 2020). "Since lupus patients are prone to infections, groups of mice were injected with viral (Imiquimod, a TLR7 agonist) or bacterial (ODN 2395, a TLR9 agonist) surrogates." (PMID 32251357, 2020). "SLC15A4 is involved in transport of oligopeptides and hydrogen ions out of the lysosome, and knockout of Slc15a4 results in abrogation of TLR7 signaling as well as amelioration of murine lupus." (PMID 31001245, 2019).